NKX2-1 (NK2 homeobox 1)
Description:
Transcription factor that binds and activates the promoter of thyroid specific genes such as thyroglobulin, thyroperoxidase, and thyrotropin receptor. Crucial in the maintenance of the thyroid differentiation phenotype. May play a role in lung development and surfactant homeostasis. Forms a regulatory loop with GRHL2 that coordinates lung epithelial cell morphogenesis and differentiation. Activates the transcription of GNRHR and plays a role in enhancing the circadian oscillation of its gene expression. Represses the transcription of the circadian transcriptional repressor NR1D1 (By similarity).
Synonyms: TTF-1; T/EBP; NKX2A; TITF1; TTF1; BCH; BHC; NK-2; NKX2.1; NMTC1; TEBP
Tractability: PROTAC: ubiquitination databases record sites on it.
Gene: Protein-coding gene on chromosome 14 (36,516,392 to 36,521,149, reverse strand). Ensembl gene ENSG00000136352.
Subcellular location: Nucleus
Subcellular location (Human Protein Atlas): Golgi apparatus; Vesicles
Gene Ontology:
Molecular function: DNA binding; DNA-binding transcription factor activity; enzyme binding; intronic transcription regulatory region sequence-specific DNA binding; protein binding; RNA polymerase II transcription regulatory region sequence-specific DNA binding; RNA polymerase II-specific DNA-binding transcription factor binding; transcription cis-regulatory region binding; DNA-binding transcription factor activity, RNA polymerase II-specific; RNA polymerase II cis-regulatory region sequence-specific DNA binding; sequence-specific DNA binding
Biological process: brain development; epithelial tube branching involved in lung morphogenesis; forebrain development; globus pallidus development; lung development; negative regulation of cell migration; negative regulation of epithelial to mesenchymal transition; negative regulation of transcription by RNA polymerase II; negative regulation of transforming growth factor beta receptor signaling pathway; positive regulation of DNA-templated transcription; positive regulation of gene expression; positive regulation of transcription by RNA polymerase II; regulation of DNA-templated transcription; response to hormone; thyroid gland development; cell differentiation; negative regulation of DNA-templated transcription; positive regulation of circadian rhythm; regulation of transcription by RNA polymerase II; animal organ development; gene expression; hypothalamus development
Cellular component: nucleus; transcription regulator complex; chromatin; nucleoplasm
Genetic constraint (gnomAD): Loss-of-function variants: 9 observed, 30.08 expected, observed/expected ratio (o/e) 0.3, 90% interval 0.18 to 0.52. The upper end of that interval is the gene's LOEUF score, 0.52, which puts it in group 2 of 6, group 1 being the genes least tolerant of losing a copy. Missense variants: 509 observed, 545.66 expected, observed/expected ratio (o/e) 0.93, 90% interval 0.87 to 1. Synonymous variants: 284 observed, 243.57 expected, observed/expected ratio (o/e) 1.17, 90% interval 1.06 to 1.29.
Gene-disease validity (ClinGen):
ClinGen rates the evidence that NKX2-1 causes each of these diseases.
NKX2-1 related choreoathetosis and congenital hypothyroidism with or without pulmonary dysfunction (autosomal dominant): Definitive. The NKX2-1 gene is located on chromosome 14 at 14q13.3 and encodes the NK2 homeobox 1 protein, a transcription factor that binds and activates thyroid specific genes.
Cancer hallmarks: escaping immune response to cancer; escaping programmed cell death (promotes); invasion and metastasis (suppresses); invasion and metastasis (promotes); change of cellular energetics; suppression of growth (promotes); proliferative signalling (promotes); angiogenesis; angiogenesis (suppresses)
Homologues: Orthologues: chimpanzee NKX2-1 (99% identical), pig NKX2-1 (97% identical), macaque NKX2-1 (96% identical), dog NKX2-1 (95% identical), rat Nkx2-1 (94% identical), mouse Nkx2-1 (91% identical), guinea pig NKX2-1 (73% identical), tropical clawed frog nkx2-1 (69% identical), zebrafish nkx2.1 (63% identical), Drosophila melanogaster scro (37% identical), Caenorhabditis elegans ceh-24 (25% identical), Caenorhabditis elegans ceh-28 (15% identical), and 4 more. Paralogues in human: NKX2-4 (52% identical), NKX2-2 (26% identical), NKX2-3 (26% identical), NKX2-5 (25% identical), NKX2-6 (24% identical), NKX2-8 (22% identical), NKX3-2 (17% identical), NKX1-1 (17% identical), NKX1-2 (16% identical), NKX3-1 (14% identical), NKX6-1 (13% identical), NKX6-2 (12% identical), and 1 more.
Diseases named in the same sentence as NKX2-1 in open-access papers:
NKX2-1 is named in the same sentence as 224 diseases in open-access papers, as found by Europe PMC text mining. Sharing a sentence is not in itself a finding about the gene and the disease. The quoted sentences say what the papers report.
lung carcinoma (120 papers, 2008 to 2026). "Further studies by other approaches will be needed to elucidate transcriptional regulation of NKX2‐1 in lung cancer development and the role of each splice variant in different genetic backgrounds." (PMID 34014042, 2021). "NKX2-1 mutations have been found in 16% of lung cancers and are associated with lung cancer metastasis." (PMID 33906647, 2021). "Kaplan–Meier analyses show that high expression of both GMIP and NKX2-1 is significantly associated with higher lung cancer patient survival." (PMID 33227088, 2020). "In contrast, in Kras mutant mice Nkx2-1 loss was shown to accelerate lung cancer (mucinous adenocarcinoma) and potentiate lung cancer metastasis." (PMID 26556242, 2015). "Recently, NKX2-1 has been linked more directly to lung cancer, where the gene locus is amplified in some cases, leading to enhanced lung cancer cell proliferation and survival." (PMID 26556242, 2015). "However, loss‐of‐function and gain‐of‐function studies in human lung carcinoma and transformed cells support a role of NKX2‐1 as an oncogene." (PMID 34014042, 2021). "Several studies report a clear association between alterations in NKX2-1 and thyroid and lung cancer, although it has also been hypothesized to play a role in the development of schizophrenia through the regulation of implicated pathways." (PMID 33414392, 2021). "However, our data suggest that permanent acquisition of a stressed transitional state, such as seen in Nkx2-1 KO organoids and Nkx2-1 KO AEPs in vivo, may drive aberrant proliferation, expression of lung cancer programs, and loss of lung identity." (PMID 38114516, 2023). "In this study, 6 hub genes,NKX2-1,CD8A,SFTA3,IL2RB,IDO1, andCXCL9, which are all M1 macrophage coexpressed genes, were utilized to build the immunotherapy response model.NKX2-1 can regulate lung cancer growth by targeting the MAPK pathway." (PMID 38379417, 2024). "From its association with SSP enzyme expression and stimulatory effect of serine synthesis from labeled glucose, also transcription factor NKX2–1 was identified as an activator of the SSP in lung cancer cells." (PMID 38515202, 2024). "We observed a superior reduction in the amount of viable immune cells, as well as reductions in the percentage of CD4+ T-cells in co-cultures with ser/gly producing NKX2-1 lung cancer cells." (PMID 38160212, 2024). "NKX2-1 serves as a marker for lung progenitors, but it has also been identified as a tumor biomarker in lung cancer due to its overexpression in adenocarcinoma." (PMID 38132167, 2023). "Exploring T-cell leukaemia, lung cancer and neuroendocrine prostate cancer patient datasets highlighted the transcription factor NKX2–1 as putative driver of serine/glycine metabolism." (PMID 36932191, 2023). "NSG mice were intravenously injected with GFP-positive vector control or NKX2–1 overexpressing A549 cells to induce orthotopic lung cancer development." (PMID 36932191, 2023). "In this study, we first systematically analyzed the expression of eight AT II-associated genes (AQP4, SFTPB, SFTPC, SFTPD, CLDN18, FOXA2, NKX2-1, and PGC) in lung cancer." (PMID 36203529, 2022). "The lncRNAs NKX2-1-AS1—located in the 14q13.3 chromosome region—and NKX2-1 protein (also known as thyroid transcription factor 1, TTF-1) are co-expressed in lung cancer, although they have distinct effects on CD274 gene (encoding PD-L1)." (PMID 36612180, 2022). "Lung cancer: Nkx2-1 is a transcription factor that suppresses malignant progression of lung adenocarcinoma." (PMID 36386843, 2022). "NKX2-1, in contrast, encodes the thyroid transcription factor-1 (TTF1) protein, which has formerly been considered a marker of lung cancer." (PMID 35109899, 2022).
lung carcinoma (continued). "SELENBP1 is regulated by Nkx2-1 in lung adenocarcinoma in both the human lung adenocarcinoma and mouse lung cancer model." (PMID 36386843, 2022). "NKX2-1 amplification and overexpression also have been proved to have contributed to lung cancer cell proliferation rates and survival results." (PMID 36203529, 2022). "In this study, we comprehensively analyzed the gene expression, prognosis value, genetic alteration, and immune cell infiltration of eight AT II-associated genes (AQP4, SFTPB, SFTPC, SFTPD, CLDN18, FOXA2, NKX2-1, and PGC) in Nonsmall Cell Lung Cancer (NSCLC)." (PMID 36203529, 2022). "NKX2-1 loss in human and murine lung adenocarcinoma leads to invasive mucinous adenocarcinoma (IMA), a lung cancer subtype that exhibits gastric differentiation and harbors a distinct spectrum of driver oncogenes." (PMID 33821796, 2021). "In prior studies of lung adenocarcinoma, we identified a circulating protein signature that reflected activation at early stages of Titf1/Nkx2-1, a known lineage-survival oncogene in lung cancer." (PMID 34439128, 2021). "NKX2-1 is a proto-oncogene contributing to lung cancer development, literature evidences are debating the role of NKX2-1 in lung cancer prognosis, our finding supports to continue to explore its role on post-IO prognosis." (PMID 33531613, 2021). "This study provides some explanation of how IMA lung cancers that lack the gene for NKX2-1 resist treatment with BRAF/MEK inhibitors." (PMID 33821796, 2021). "TBX5, SPRED2, and NKX2-1 have been shown to exhibit tumor suppressor functions in lung cancer, while GMIP function has yet to be determined in cancer cells." (PMID 33227088, 2020). "Carriers of mutations in TITF1/NKX2-1 can have increased risk of malignancy, specifically lung cancer, and should undergo appropriate screening." (PMID 32832197, 2020). "NKX2-1 has been shown to play a critical role in lung development, lung cancer differentiation and morphogenesis, particularly in LUAD." (PMID 33086649, 2020). "Lastly, when the genes for NKX2-1, FoxA1 and FoxA2 were deleted later, in lung tumors that had already formed, the outcome was a more aggressive type of lung cancer that also occurs in human patients." (PMID 30475207, 2018). "Previously, we and others demonstrated that Kras lung cancer mouse models with reduced expression of Nkx2‐1 (KrasG12D; Nkx2‐1+/− or KrasG12D; Nkx2‐1flox/flox) developed mucinous lung tumors mimicking human IMA." (PMID 28255028, 2017). "In this study, we have developed an accurate lung cancer diagnostic test based on the expression analysis of embryonic versus adult isoforms of two genes (GATA6, NKX2‐1) in exhaled breath condensates." (PMID 27821429, 2016). "Our results provide new insight into the mechanisms of NKX2-1 mediated lung cancer, and a dataset for continued exploration." (PMID 26556242, 2015). "In tumors, NKX2-1 has oncogenic and tumor suppressor functions, depending on the cell context, suggesting a dual role as a lineage specific factor contributing to lung cancer progression." (PMID 25763778, 2015). "NKX2-1 likely plays distinct roles in the context of EGFR-driven and KRAS-driven lung cancers, with Egfr-driven murine tumors perhaps more closely modeling NKX2-1 amplified human lung cancer." (PMID 26556242, 2015). "Many of these aberrations were specific to the primary tissue of origin of the cancer, for example, lung developmental transcription factor NKX2-1 in lung cancer, AURKA in colon cancer and AR in prostate cancer." (PMID 25889064, 2015). "Here, to uncover oncogenic mechanisms in human lung cancer, we carried out a combined transcriptome (NKX2-1 knockdown followed by RNAseq) and cistrome (NKX2-1 binding sites by ChIP-seq) analysis in NKX2-1 amplified NSCLC cell lines." (PMID 26556242, 2015).
lung carcinoma (continued). "In lung cancer NKX2-1 performs the role of a lineage-specific oncogene enhancing proliferation and survival." (PMID 23637834, 2013). "Overexpression of NKX2-1 mediated by genomic amplification enhances tumorigenicity of lung cancer cells as evidenced by colony formation of lung epithelial cells and advanced malignancy in affected patients." (PMID 23637834, 2013). "MUC1, a physiological marker, HIF1A, a regulator of metabolic reprogramming, and NKX2-1, a lineage-specific marker performed well as classifiers of lung cancer and its major subtypes." (PMID 23028920, 2012). "Multiple evidences support a dual role for NKX2-1 as a proto-oncogene and tumor suppressor gene in lung cancer." (PMID 22242187, 2012). "NKX2-1 has been found frequently amplified and overexpressed in AdCa and is an established marker of lung-cancer lineage used to distinguish AdCa from the more centrally located SqCC." (PMID 23028920, 2012). "NKX2-1 was also proposed as a suppressor of lung adenocarcinoma progression in a mouse model of lung cancer." (PMID 22242187, 2012). "That is, the smoking-gene interaction means that some smokers are at greater risk of developing lung cancer, with several host characteristics (i.e., K-ras, GSTM1, CYP2D6, c-MET, NKX2-1, LKB1, BRAF) implicated in lung cancer onset." (PMID 20843376, 2010). "Two such genes are the melanoma-specific oncogene MITF, which is selectively amplified and overexpressed in 20% of melanomas, and NKX2-1, which lies in the minimal amplified region of a lung-cancer-specific 14q13.3 amplicon found in up to 20% of lung cancers." (PMID 19285540, 2009). "Nonetheless, other cell lineage-specific transcription factors have been found amplified in cancers, including MITF in melanoma, AR in hormone-independent prostate cancer, ESR1 in breast cancer, and most recently NKX2-1 (TITF) in lung cancer." (PMID 18535672, 2008). "HDAC3, one of chidamide’s targets, has been implicated in chemoresistance in various malignancies: it is essential for Kras-mutant lung cancer progression by co-regulating transcription with NKX2-1 and promoting FGFR1 expression, with its inhibition restoring trametinib sensitivity." (PMID 41326348, 2025). "Additionally, NKX2-1 involvement in lung cancer pathogenesis underscores its significance as a biomarker for distinguishing primary lung adenocarcinomas from other pulmonary conditions." (PMID 40395234, 2025). "Those with NKX2-1-RD present diverse respiratory conditions, spanning from neonatal respiratory distress to various severe lung diseases, including interstitial lung disease and lung cancer." (PMID 40395234, 2025). "We then analyzed the expression of the lung cancer lineage specifiers NKX2-1 and SOX2." (PMID 38093367, 2023). "On the other hand, NKX2-1 is amplified and a suggested oncogene in human lung cancer." (PMID 37534159, 2023). "It is noteworthy that whereas NKX2-1 is an established lung cancer gene with pleiotropic actions, it is unknown to what extent, if any, Nkx2-1 might influence carcinogenesis and tumor progression in the thyroid gland." (PMID 37534159, 2023). "NKX2-1 may control lung cancer progression through the induction of DUSP6, an ERK phosphatase, to decrease ERK activity." (PMID 35991889, 2022). "Furthermore, approximately 70% of lung adenocarcinomas (LADs) express TTF‐1 independent of disease stage and retain features of the TRU to a certain extent, strongly suggesting that NKX2‐1/TTF‐1 is a potential lineage survival oncogene in lung cancer." (PMID 34014042, 2021). "NKX2-1 has both pro- and anti-oncogenic activities in lung cancer." (PMID 34748583, 2021). "Specifically, FOXA1 plays a significant role in non-small cell lung cancer, MEF2 family members have a role in lung carcinoma, TEAD family members have known roles in carcinogenesis of epithelial tissues, and NKX2–1 has a long history of involvement in lung cancer, COPD and IPF." (PMID 34922464, 2021).